MFGE8 (milk fat globule EGF and factor V/VIII domain containing)
Diseases named in the same sentence as MFGE8 in open-access papers (continued):
Sharing a sentence is not in itself a finding about the gene and the disease.
Insulin resistance (3 papers, 2022 to 2024). Increased resistance towards insulin, that is, diminished effectiveness of insulin in reducing blood glucose levels. "MFGE8 binds the αvβ5 integrin, increasing the association of αvβ5 with the insulin receptor and resulting in insulin resistance through reduced phosphorylation/activation of the insulin receptor signaling pathway." (PMID 38199575, 2024). "Genes commonly upregulated in the IR-iPSCs when compared to each IS-iPSC group include EGR1 and MFGE8, which were previously associated with insulin resistance, as well as CD74, SEMA6B, SLFN13, TMEM151B, SLC22A17, and AGRN." (PMID 35987697, 2022). "Additional studies of interest include two cohorts of patients from China, one with T2D, and one with gestational diabetes in whom serum MFGE8 levels correlate with multiple indices of insulin resistance." (PMID 38199575, 2024). "Global Mfge8 KO mice develop insulin resistance concomitant with the development of differences in body fat composition at 10 weeks of age." (PMID 38199575, 2024). "Despite relatively modest sample sizes, these four cohorts validate our mechanistic work in mice indicating a role for MFGE8 in inducing insulin resistance and lay the foundation for therapeutic targeting of this pathway to ameliorate insulin resistance." (PMID 38199575, 2024). "Serum MFGE8 levels correlate with markers of insulin resistance in two diabetic cohorts of patients from China, one with gestational diabetes and one with T2D mellitus." (PMID 38199575, 2024). "In humans, a growing body of literature links MFGE8 with insulin resistance." (PMID 38199575, 2024).
ischemia (3 papers, 2020 to 2025). A hypoperfusion of the BLOOD through an organ or tissue caused by a PATHOLOGIC CONSTRICTION or obstruction of its BLOOD VESSELS, or an absence of BLOOD CIRCULATION. "Cardiomyocyte ischemia plays a critical role in the development of SCM, so we propose that MFGE8 may play an important role in SCM by participating in the process of myocardial ischemia." (PMID 32695227, 2020).
Obesity (3 papers, 2022 to 2024). Accumulation of substantial excess body fat. "The effect of obesity on the insulin-MFGE8-β5-PTP1B pathway we have described remains to be determined." (PMID 38199575, 2024). "MFGE8 is an integrin ligand that promotes uptake of fatty acids leading to obesity." (PMID 35987697, 2022).
sarcopenia (3 papers, 2022 to 2024). Progressive decline in muscle mass due to aging which results in decreased functional capacity of muscles. "Given its pivotal role in multiple physiological processes, the development of drugs targeting the MFGE8 gene might offer potential therapeutic advantages for the treatment of sarcopenia." (PMID 38644354, 2024). "The results revealed that six potential druggable genes (HP, HLA‐DRA, MAP 3K3, MFGE8, COL15A1, and AURKA) passed the colocalization analysis and were present in more than one QTL datasets or sarcopenia‐related traits." (PMID 38644354, 2024). "Based on these integrated datasets, our study provides potential evidence for the genetic colocalization of six drug target genes (HP, HLA‐DRA, MAP 3K3, MFGE8, COL15A1, and AURKA) with sarcopenia." (PMID 38644354, 2024). "Except for MFGE8, formulations related to the other five genes have been evaluated in clinical trials for other diseases, but none have yet been used for the treatment of sarcopenia." (PMID 38644354, 2024). "Our research indicated MAP 3K3, MFGE8, COL15A1, HP, and HLA‐DRA may serve as promising targets for sarcopenia, while the effectiveness of zinc supplementation and collagenase clostridium histolyticum for sarcopenia requires further validation." (PMID 38644354, 2024).
amyloid (2 papers, 2017 to 2025). "Given its role in amyloid pathology, MFGE8 is under investigation as a therapeutic target for preventing Aβ-driven neurodegeneration." (PMID 40602528, 2025).
breast tumor (2 papers, 2013 to 2025). "CD109, AHNAK2, and MFGE8 in breast BRCA1-mut cancers, and B3GNT7, CTSV, and GSDMC in BRCA2-mut breast tumors." (PMID 40647506, 2025). "Finally, to determine whether new MFGE8-blocking agents, such as the antibodies identified above, could be used for treatment of other tumors, we analyzed MFGE8 expression by immunohistochemistry in our collection of breast tumor biopsies generated from patients treated at Institut Curie." (PMID 23977342, 2013).
cerebrovascular disease (2 papers, 2020 to 2022). "Previous studies indicate that MFGE8 is under‐express in cardiovascular and cerebrovascular diseases." (PMID 32945126, 2020).
colon cancer (2 papers, 2016 to 2022). "In an interesting study using Mfge8 KO mice, the authors used two different models of colon cancer, and evaluated the role of lactadherin and αv-integrin in epithelial and tumor cell proliferation." (PMID 35409215, 2022). "To further confirm this interaction, we evaluated cell adhesion of SW480 cells, a human colon cancer cell line, transfected with α8 or β3 to Mfge8." (PMID 27092791, 2016).
mastitis (2 papers, 2009 to 2023). Inflammation of breast tissue during lactation or postpartum due to an obstructed duct or infection. "Bovine orthologs of the Mfge8 and Lpar3 associated with mastitis phenotypes in knockout and transgenic mouse models were also reported differentially expressed during mammary infection in cattle." (PMID 36759924, 2023). "In the MGI database, we found one gene disruption (Mfge8) and five transgenic mouse models for Lao1, Enpp2, Lpar1, Lpar2, and Lpar3 that resulted in abnormal mammary gland physiology and were also associated with mastitis." (PMID 36759924, 2023).
pancreatitis (2 papers, 2013 to 2021). Inflammation of the pancreas. "To test this hypothesis, we examined the role of MFG-E8 in pancreatic inflammation using an animal model of pancreatitis and Mfge8-deficient mice." (PMID 33806041, 2021). "Only mild acinar regeneration was observed throughout the course of cerulein-induced pancreatitis in Mfge8 KO mice." (PMID 33806041, 2021). "During pancreatitis, Mfge8 transcripts were abundantly expressed in acinar cells and endothelial cells in addition to ductal epithelial cells." (PMID 33806041, 2021). "At 24 h after induction of pancreatitis by cerulein, Mfge8 mRNA signals were localized to ductal epithelial cells and acinar cells in pancreas." (PMID 33806041, 2021). "In the present study, we found that acinar regeneration after pancreatitis is impaired in Mfge8 KO mice, and that treatment of these mice with rMFG-E8 partially protects against pancreatic injury during the acute phase and restores acinar regeneration and repair." (PMID 33806041, 2021). "We administered cerulein to wild-type (WT) and Mfge8 knockout (KO) mice to induce pancreatitis." (PMID 33806041, 2021). "However, in situ hybridization did not reveal Mfge8 gene expression in pancreatic islets of sham-treated mice or during cerulein-induced pancreatitis." (PMID 33806041, 2021).
retinal degeneration (2 papers, 2012 to 2013). Degeneration of the retina. "Although MFGE8 deficiency did not lead to retinal degeneration, disturbances in RPE biology and diminished expression of trophic factors can lead to choroidal involution." (PMID 22438901, 2012).
type 2 diabetes (2 papers, 2016 to 2019). "There was a report that the level of MFGE8 in the blood of patients with type 2 diabetes was higher than HSs24." (PMID 31811237, 2019).
ulcerative colitis (2 papers, 2023 to 2025). An inflammatory bowel disease involving the mucosal surface of the large intestine and rectum. "MFGE8 levels are decreased in patients with ulcerative colitis (UC) compared with healthy controls and are associated with increased disease activity, highlighting the importance of MFGE8 in intestinal disease." (PMID 36538527, 2023). "Through the establishment of ulcerative colitis animal models combined with RNA-seq and ASTRAL-DIA proteomic analyses, we validated that specific hub genes, including Anxa1, Cd93, and Mfge8, exhibited consistent alterations at both the transcriptional and protein levels." (PMID 41050686, 2025).
atrial fibrillation (1 paper, 2020). A disorder characterized by an electrocardiographic finding of a supraventricular arrhythmia characterized by the replacement of consistent P waves by rapid oscillations or fibrillatory waves that vary in size, shape and timing and are accompanied by an irregular ventricular response. "In our previous study, we found the protective role of MFGE8 in attenuating Ang‐II‐induced atrial fibrosis and atrial fibrillation through TGF‐β1‐Smad2/3 pathway." (PMID 32945126, 2020). "In our previous work, MFGE8 suppressed atrial fibrosis via TGF‐β1/Smad2/3 pathway in an integrinβ3‐dependent way and attenuated the vulnerability to atrial fibrillation." (PMID 32945126, 2020).
chronic kidney disease (1 paper, 2022). Impairment of the renal function secondary to chronic kidney damage persisting for three or more months. "For example, elevated expression of MFGE8 was positively correlated with aortic stiffness in chronic kidney disease patients, and increased GAS6 levels in serum have been observed to correlate with elevated BP and age-related vascular remodeling in mice." (PMID 34929167, 2022).
chronic prostatitis (1 paper, 2019). An infectious or non-infectious chronic inflammatory process that affects the prostate gland. "Hic1, Zfp148, and Mfge8 gene mutations were detected in chronic prostatitis somatic cells." (PMID 31088536, 2019).
coronary artery stenosis (1 paper, 2021). "Additionally, MFGE8 level decreases in the CHD group and is negatively associated with the severity of coronary artery stenosis and the risk of clinical events." (PMID 34950025, 2021).
coronary atherosclerosis (1 paper, 2022). Atherosclerosis of the coronary vasculature. "A genome-wide association study identifies MFGE8 as protective against coronary atherosclerosis in European and East Asian populations." (PMID 35978133, 2022). "In addition to MFGE8, we identified three additional previously unreported loci to be associated with coronary atherosclerosis, TMEM200A, PRG3 and FHL1 being the nearest genes of the lead variants." (PMID 35978133, 2022). "In addition to inframe insertion rs53412514, we identified a splice acceptor variant (rs201988637) in MFGE8 to be associated with coronary atherosclerosis (OR = 0.72 [0.63–0.83], p = 7.94 × 10−06) and multiple disease endpoints representing major CHD." (PMID 35978133, 2022). "Additionally, we identified a protective association between splice acceptor variant rs201988637 in MFGE8 and coronary atherosclerosis, independent of the rs534125149, with no significant risk-increasing associations." (PMID 35978133, 2022).
coronary heart disease (1 paper, 2022). "Previously, common intergenic variant (rs8042271) near MFGE8 has been reported to associate with coronary heart disease (CHD) risk." (PMID 35978133, 2022). "Splice acceptor variant rs201988637 in MFGE8 was also associated with lower pulse pressure, but not with blood lipids, blood pressure or other known coronary heart disease risk factors." (PMID 35978133, 2022). "First, MFGE8 is a potential intervention target with specific effects on coronary heart disease." (PMID 35978133, 2022).
enteritis (1 paper, 2022). Inflammation of the small intestine. "A growing number of studies have shown the remarkable change of MFGE8 expression in intestinal mucosa of enteritis mice, presenting an obvious anti-inflammation function." (PMID 35674581, 2022).
gastric cancer (1 paper, 2021). A primary or metastatic malignant neoplasm involving the stomach. "In addition, we selected the serum of 80 ECs, 80 HCCs, and 80 LCs and measured the titer of four TAAbs (anti-MFGE8, anti-NRAS, anti-PTP4A1, anti-RRAS2) by ELISA to verify the specificity of four TAAbs in gastric cancer." (PMID 33718231, 2021).
giant cell arteritis (1 paper, 2024). "Furthermore, in the present study, the scope of evidence indicating the participation of this pathway in giant cell arteritis has been expanded through the observed association between VTN and MFGE8 and this type of vasculitis." (PMID 38734017, 2024). "Additionally, three new genomic associations with giant cell arteritis were identified at the 8p21.1 (CCDC25, rs11782624; p=1·28 × 10–8; OR 1·18 [95% CI 1·12–1·25]), 15q26.1 (MFGE8, rs8029053; p=4·96 × 10–8; OR 1·19 [1·12–1·26]) and 17q11.2 (VTN, rs704; p=2·75 × 10–9; OR 0·84 [0·79–0·89]) regions." (PMID 38734017, 2024).
heart failure (1 paper, 2020). Inability of the heart to pump blood at an adequate rate to meet tissue metabolic requirements. "We can speculate that the administration of rh‐MFGE8 prior to cardiac fibrosis may have clinical implications for inhibiting the progress of cardiac remodelling or even heart failure." (PMID 32945126, 2020). "Our research demonstrates a novel molecular mechanism of the function of MFGE8 in EndMT and further proves the use of MFGE8 as a potential circulating biomarker or therapeutic target for diagnosis and mitigation of CF and CF‐related heart failure." (PMID 32945126, 2020).
influenza (1 paper, 2016). An acute viral infection of the respiratory tract, occurring in isolated cases, in epidemics, or in pandemics; it is caused by serologically different strains of viruses (influenzaviruses) designated A, B, and C, has a 3-day incubation period, and usually lasts for 3 to 10 days. "Of the proteins with reduced expression identified in our study, the five most-reduced DEPs in samples from influenza-infected patients that were also correlated with higher viral loads were CTSD, KLK7, MFGE8, MAPK9 and CD27, respectively." (PMID 27088501, 2016).
kidney stones (1 paper, 2024). "However, there are few studies to reveal the role of MFGE8 in the modulation of kidney stones." (PMID 39725663, 2024). "According to the references, MFGE8 was related to autophagy in early brain injury (PMID: 38095841) and pancreatic fibrosis (PMID: 34421598); however, whether it is associated with autophagy aggravated by LA in kidney stones remains unknown." (PMID 39725663, 2024).
meningioma (1 paper, 2025). A generally slow growing tumor attached to the dura mater. "ROC analyses showed that the AUC values for DJ-1 and GDF15 were below 0.7, with p-values above 0.05, whereas the MFGE8 gene demonstrated an AUC value above 0.7 with a p-value below 0.05, indicating that only MFGE8 has potential diagnostic discriminatory power for tumour diameter in meningioma." (PMID 41009755, 2025). "Additionally, the observed associations of DJ-1 and MFGE8 expression with histological grade and proliferative activity indicate that these genes may contribute to the evaluation of malignancy potential in meningiomas." (PMID 41009755, 2025). "The expression levels of the DJ-1, GDF15, and MFGE8 genes in meningioma patients were elevated compared to those in the control group." (PMID 41009755, 2025). "In this context, MFGE8 may interact not only with tumour-intrinsic factors such as histologic grade but also with microenvironmental components, potentially influencing meningioma behaviour in a broader biological framework." (PMID 41009755, 2025). "Therefore, further comprehensive studies are required in order to elucidate the prognostic significance and mechanistic roles of MFGE8 in meningiomas." (PMID 41009755, 2025). "Therefore, examining gene expression levels across these subgroups may offer a framework for assessing the potential of DJ-1, GDF15, and MFGE8 to discriminate between benign and atypical meningiomas and their possible functional roles in tumour biology." (PMID 41009755, 2025). "In meningioma patients, the expression levels of the DJ-1, GDF15, and MFGE8 genes were significantly higher in Grade II tumours compared to Grade I tumours." (PMID 41009755, 2025). "In meningioma patients, the expression levels of DJ-1, GDF15, and MFGE8 genes were elevated in tumours larger than 3 cm compared to smaller tumours and the control group." (PMID 41009755, 2025). "In meningioma patients, DJ-1, GDF15, and MFGE8 gene expression levels were significantly elevated in tumours with Ki-67 Pi > 5% compared to those with Ki-67 Pi ≤ 5% (DJ-1, GDF15, and MFGE8; p = 0.015, p = 0.003, and p = 0.012, respectively)." (PMID 41009755, 2025). "ROC analyses for meningioma cases revealed that the AUC values for these genes were all below 0.7, with p-values above 0.05, indicating that DJ-1, GDF15, and MFGE8 do not have sufficient diagnostic discriminatory power based on patient sex in meningioma." (PMID 41009755, 2025).
metastatic melanoma (1 paper, 2021). A melanoma that has spread from its primary site to another anatomic site. "Together, these results suggest the therapeutic potential of targeting MDSCs or MFGE8 for metastatic melanoma or other cancers." (PMID 34440100, 2021).
pancreatic cancer (1 paper, 2014). "The other anchor protein, MFGE8, expression also varied in a broad range across the PDAC cell lines, therefore, it is not useful to efficiently isolate pancreatic cancer specific EVs from the body fluids of PDAC patients." (PMID 25469109, 2014).
short bowel syndrome (1 paper, 2016). "Activation of the pathway we describe with recombinant Mfge8 could be used to treat disorders characterized by increased gastrointestinal transit time and malabsorption such as short bowel syndrome." (PMID 27092791, 2016).
stress-related disorder (1 paper, 2025). Stress-related disorders are mental health disorders that are a result of an atypical response to both short and long-term anxiety due to physical, mental, or emotional stress. "bHR-like animals also had upregulation of protective Mfge8 and upregulation of Nqo2, which can enhance reactive oxygen species production or reduce oxidative stress in a manner important for encoding novelty in hippocampal interneurons and potentially stress-related disorders." (PMID 40103584, 2025).
tauopathies (1 paper, 2018). "MFGE8 expression is elevated in transgenic P301S-tau mouse brains with tau inclusions and in tauinclusion-rich brain regions of several human tauopathies, indicating shared mechanisms of disease." (PMID 30134156, 2018). "No increase in MFGE8 was found in thecortex or cerebellum of C9orf72 cases, consistent with the specific expression of MFGE8 in tauopathies and strengthening therelevance of our findings in P301S mice for human disease." (PMID 30134156, 2018).
ulcer (1 paper, 2023). "Therefore, MFGE8 might inhibit the infiltration of macrophages and inflammatory response in the ulcer site and promote the proliferation of fibroblasts and wound repair in the process of PU repair." (PMID 38017428, 2023).